GDF15 (growth differentiation factor 15)
Diseases named in the same sentence as GDF15 in open-access papers (continued):
Sharing a sentence is not in itself a finding about the gene and the disease.
mitochondrial disease (continued). "Additionally, this suggests that FGF21 and GDF15, which are biomarkers of mitochondrial diseases, could be used to follow treatment responses and disease progression/recovery in patients with mitochondrial disease." (PMID 33128823, 2020). "It has been confirmed that translational defects in mitochondrial and nuclear DNA, typically seen in mitochondrial diseases involving skeletal muscle, lead to increased FGF21/GDF15 levels." (PMID 39124668, 2024). "GDF15 is a cytokine that is transcriptionally activated by the ISR, which is frequently activated in the heart in mitochondrial diseases." (PMID 37260376, 2023). "Changes in serum levels of Fibroblast-growth-factor 21 (FGF-21) and Growth-differentiation-factor 15 (GDF-15) are characteristic of some metabolic and mitochondrial diseases." (PMID 36935492, 2023). "We found statistically significant differencesbetween mean GDF-15 levels in patients with PMM and those inpatients with CFS, and also between patients with PMM and in patients with non-mitochondrial disease (p = 0.0001 and p = 0.0101, respectively)." (PMID 36983435, 2023). "As non-invasive and economical steps in the diagnosis of a mitochondrial disease, the peptide molecule fibroblast-growth-factor-21 (FGF-21) and growth-differentiation-factor-15 (GDF-15) are established biomarkers." (PMID 34572118, 2021). "The potential of GDF-15 as a MM biomarker was evaluated using AUROC, which was previously reported to be 0.8228 and 0.9927 in mitochondrial disease patients." (PMID 35071983, 2021). "Similar to other studies using PPAR agonists, we observed dose‐dependent increases in serum GDF‐15 and FGF‐21, which have been proposed as biomarkers of mitochondrial disease." (PMID 32107855, 2020). "Next, to determine the gene expression changes in treated blasts, we performed qPCR analyses of Growth Differentiation Factor 15 (GDF15), which is a biomarker for mitochondrial diseases or oxidative stress, as well as of a group of nuclear TFs responsible for blast survival and metabolic adaptation." (PMID 39126100, 2024). "Recently, blood levels of growth differentiation factor-15 (GDF-15) have been described as a biomarker to diagnose mitochondrial dysfunction, with an estimated average sensitivity vs. specificity of 89.7% to identify primary mitochondrial disease patients." (PMID 34048486, 2021). "In a recent study, plasma GDF15 concentrations were assessed in patients with genetically confirmed primary mitochondrial disease and patients with non-mitochondrial inherited diseases." (PMID 34445593, 2021). "For non-muscle affected mitochondrial diseases, the relation with plasma GDF-15 levels is less clear." (PMID 34048486, 2021). "Growth differentiation factor 15 (GDF15) and fibroblast growth factor 21 (FGF21) are representative metabokines that are responsive to mitochondrial diseases, and their expression is stimulated through ATF4, CHOP, and XBP1, key components of the integrated stress response." (PMID 33718833, 2021). "On the other hand, GDF15 seems to be more indicative of mitochondrial diseases regardless of clinical phenotype, whereas FGF21 sensitivity for mitochondrial diseases is higher when muscle manifestations are present." (PMID 32397676, 2020). "We note pyruvate therapy, which serves to regenerate NAD+, was recently shown to decrease serum GDF15, a circulating marker of the ISR, in mitochondrial disease patients, providing rich in vivo support for our identification of NADH imbalance as a trigger of the ISR." (PMID 32463360, 2020). "However, this was accompanied by an increase in serum biomarkers of mitochondrial disease, including fibroblast growth factor 21 (FGF‐21), growth and differentiation factor 15 (GDF‐15), plus dysregulation of fatty acid and amino acid metabolism." (PMID 32107855, 2020).
mitochondrial disease (continued). "Besides the traditional marker of OXPHOS dysfunction, the pathological increase of lactic acid, promising biomarkers for mitochondrial disease have been recently proposed, including fibroblast growth factor 21 (FGF21), GDF-15, and creatine." (PMID 32851462, 2020). "Interestingly, a combined evaluation of both GDF-15 and FGF-21 in serum from adult patients with mitochondrial disease did not improve the diagnostic value of the individual tests." (PMID 38515869, 2024). "Furthermore, GDF-15 is indicative of mitochondrial disease regardless of the phenotype, whereas FGF-21 appears to better identify patients with muscle manifestations." (PMID 36983435, 2023). "We found mRNA expression of Fgf21 and Gdf15, which are markers of mitochondrial disease, but could not show any improvement with NMN administration." (PMID 37793777, 2023). "While there is currently no reliable biomarker for the screening or diagnosis of mitochondrial diseases (MDs), GDF15 may be a useful novel biomarker for the specific screening of MDs because its measurement involves a less-invasive approach than muscle biopsy." (PMID 34445593, 2021). "However, GDF15 did not correlate with disease severity within mitochondrial disease groups." (PMID 40019842, 2025). "A combined urinary biomarker panel—including stress markers (GDF15, CYCS, and PRDX2), immune effectors (MPO and C4A), ECM proteins (COL1A1 and CCN2), and selected amino acids—could support diagnosis, patient stratification, and longitudinal monitoring in mitochondrial disease." (PMID 41373442, 2025). "Growth Differentiation Factor 15 (GDF-15), previously proposed to be a potential biomarker of mitochondrial disease, was 1,655 ± 262.2 pg/mL (Mayo Clinic Laboratories, normal ≤ 750 pg/mL) in MM (n = 44) and 524.9 ± 50.7 pg/mL in the Unlikely group (n = 20), p = 0.003." (PMID 35071983, 2021). "The study used a healthy group of children without mitochondrial disease and compared them to those with MRC; results suggested that FGF21 outperforms GDF15 when discriminating between both groups." (PMID 35806492, 2022). "In our cross-sectional analysis of CPHIV who did or did not meet clinical definitions of “possible” mitochondrial disease, we found significantly higher plasma levels of the mitokines FGF21 and/or GDF15 in those with MDC score ≥3." (PMID 34972147, 2021).
kidney disease (64 papers, 2013 to 2026). "It was indeed shown that serum GDF15 levels in patients with renal diseases are elevated and are associated with comorbidities and pathological features." (PMID 38892145, 2024). "Previous studies reported elevated serum levels of GDF15 in patients with kidney disorder, and its association with kidney disease progression, while other studies identified GDF15 to have protective effects." (PMID 38607075, 2024). "GDF-15 is generally increased in patients with kidney disease and associated with dialysis vintage in hemodialysis patients." (PMID 33419237, 2020). "Our experimental study with GDF15-deficient mice proves the strong impact of the protein on the outcome of kidney disease and shows increased systemic and kidney expression of GDF15 during experimental GN." (PMID 32977372, 2020). "For instance, recent investigations of two independent cohorts showed that systemic GDF15 levels correlate with the intrarenal expression of GDF15 and are significantly associated with the progression of kidney disease." (PMID 32977372, 2020). "We found that elevated GDF-15 (≥2.15 ng/ml) was independently associated with a high risk of renal disease progression as defined as a 30% decline in eGFR or the development of ESRD, even after adjusting for additional risk factors in IMN." (PMID 29682097, 2018). "Although growth differentiation factor 15 (GDF15) has been implicated in kidney diseases, its specific relationship and mechanisms in the context of renal TIF remain unclear." (PMID 41474228, 2026). "GDF15 is a strong prognosticator of all‐cause mortality in adults with heart disease or on haemodialysis, but additional studies are needed to better characterize GDF15's role as a biomarker or mediator of paediatric cardiac and renal disease." (PMID 40019842, 2025). "Growth-differentiation factor-15 (GDF-15) is a cytokine with a yet unclear function, but a quite ubiquitous distribution in human tissues and whose increase is associated with cardiac, pulmonary, and renal diseases." (PMID 34202603, 2021). "This is important because GDF15 has been linked to the onset and progression of kidney disease." (PMID 32375259, 2020). "The knowledge of associations between GDF-15 and renal disease has been increasing." (PMID 32089755, 2020). "GDF15 is increased in patients with kidney disease and is associated with dialysis vintage." (PMID 32375259, 2020). "Until now, several studies showed that GDF15 is associated with a rapid decline in kidney function, suggesting that might be a useful predictor for the development of kidney disease." (PMID 32977372, 2020). "However the mechanisms’ underlying the associations between FGF-23 and GDF-15 on one side and mortality and renal disease on the other remains unclear." (PMID 29698460, 2018). "The sensitivity and specificity of GDF-15 in predicting contrast-induced nephropathy differ among various studies." (PMID 40243457, 2025). "The mouse model of PAN-induced podocyte injury revealed that, indeed, GDF15 demonstrates a protective effect on kidney disease by mitigating the infiltration of immune cells into glomeruli and reducing proteinuria." (PMID 38607075, 2024). "GDF-15 is also known to be elevated in various kidney diseases and recent studies have suggested that GDF-15 is a prognostic marker of disease progression and mortality in CKD patients." (PMID 35204349, 2022). "GDF-15 regulates and involves in a variety of cellular functions, including cardiovascular, metabolism, and kidney diseases." (PMID 35963873, 2022). "There are two possible explanations for an increase in the level of GDF15 during renal diseases, either less clearance or increased synthesis of GDF15 or both." (PMID 33567936, 2021). "Due to the interdependency of heart and kidney, several studies have explored kidney disease in relation to cardiovascular biomarkers, among which the predictive value of growth differentiation factor 15 (GDF-15) was recognized." (PMID 34706669, 2021).
kidney disease (continued). "Previously, we also reported that in patients ≥65 years, serum concentrations of GDF-15 were significantly higher in comparison with the younger group of patients with early stages of kidney disease." (PMID 34442028, 2021). "This suggests that GDF-15 is involved in the prognosis and pathogenesis of various kidney diseases as well as AKI." (PMID 34441955, 2021). "Increasing data exists on GDF-15 in children, but only one study on children with kidney disease is published and demonstrates elevated GDF-15 levels in patients on hemodialysis and peritoneal dialysis." (PMID 32089755, 2020). "Although GDF-15 protects against renal injury, a high GDF-15 is associated with severe renal injury and a poor prognosis of renal disease, as also seen in the heart." (PMID 29682097, 2018). "Studies on renal injury in animal models suggest two possible reasons for increase in GDF-15 levels during renal diseases; either GDF-15 is less cleared from the circulation by the kidneys or synthesis of GDF-15 is increased in renal diseases, or both." (PMID 26273671, 2015). "In adults without known kidney disease followed in the Framingham Heart study, higher serum GDF-15 concentrations were associated with a greater risk of developing CKD." (PMID 41141543, 2025). "Data on GDF-15 in children with kidney disease have been limited and inconclusive." (PMID 41141543, 2025). "Similarly, in renal disorders, GDF-15 reduces tubular damage by modulating oxidative stress and inflammatory pathways." (PMID 39781722, 2025). "Patients in the high serum GDF-15 had more severe kidney disease and lower eGFR." (PMID 39781722, 2025). "GDF-15 has been reported as an early biomarker of kidney disease." (PMID 39000435, 2024). "GDF-15, a key regulator in aging, is known for its roles in reducing systemic inflammation, supporting mitochondrial function, and managing energy homeostasis, thus acting as a biomarker for age-related conditions and cardiovascular and renal diseases." (PMID 39772209, 2024). "Previous studies showed correlations between GDF-15 and various kidney disease." (PMID 35204349, 2022). "For instance, GDF-15 was found to predict estimated glomerular filtration rate (eGFR) decline and mortality in type 1 diabetic patients with nephropathy, mortality in ESRD, eGFR decline and progression to ESRD in CKD, and progression to dialysis and mortality in light chain amyloidosis." (PMID 34706669, 2021). "GDF-15 has been reported as a biomarker in several kinds of pathologies, including kidney disease." (PMID 34943605, 2021). "In humans, there are few studies linking GDF15 to kidney disease." (PMID 32375259, 2020). "As all the patients in our study suffered from advanced stages of kidney disease, we could hypothesize that the differences seen in GDF-15 levels come from the expression in other locations, such as myocardium or vascular tissue." (PMID 33419237, 2020). "However, the suitability of GDF15 as a precise marker for kidney disease needs further investigation." (PMID 32977372, 2020). "This increase in GDF15 levels during kidney diseases is associated with the increased production of GDF15 in response to stress (unpublished data) rather than with decreased protein clearance from circulation." (PMID 32977372, 2020). "Moreover, its role as a urinary marker on the progression of kidney disease, as well as the correlation of plasma and urine GDF15 levels, needs to be elucidated." (PMID 32977372, 2020). "This indicates a more direct role of GDF-15 in the renal disease process." (PMID 29698460, 2018). "Thus, overexpression of GDF15 can both positively and negatively regulate kidney disease." (PMID 40854626, 2025). "Renin, GDF15, PRSS8, RARRES2, PGLYRP1, LOX1, and UPAR, all robustly related to PA, have been related to cardiovascular or kidney disease via different pathways." (PMID 40498722, 2025).
kidney disease (continued). "Although significant evidence shows the importance of GDF-15 in metabolism and appetite regulation, very few in vivo studies have focussed on the role of GDF-15 in cardiovascular and renal disorders." (PMID 39781722, 2025). "To investigate the effect of GDF15 on the glomerular inflammatory response, we first examined the infiltration of immune cells in the glomeruli in PAN-induced kidney disease." (PMID 38607075, 2024). "Growth differentiation factor 15 (GDF15) is a protein which is upregulated as consequence of organ injury, as seen in heart and kidney disease." (PMID 34372849, 2021). "At the early time point (24 h), CDKN1A (p21CIP1) a gene known to stop cell-cycle progression was the most strongly up-regulated gene, followed by GDF15, a member of the TGF beta superfamily reported to be elevated in patients with renal diseases." (PMID 23457584, 2013). "However, consistently elevated levels of GDF-15 correlate with the progression of CKD, accelerated decline in renal function, and poorer prognosis across various renal disorders." (PMID 40243457, 2025). "In this context, the connection between elevated GDF-15 concentrations, diminished renal function, and inflammatory activity in patients with GA supports a potential protective or compensatory role for GDF-15 in the progression of kidney disease." (PMID 40722837, 2025). "Together, lack of GDF15 induces severe renal disease upon anti-GBM serum treatment, whereas control mice (WT anti-GBM) displayed a less severe phenotype." (PMID 32977372, 2020). "Together, the systemic lack of GDF15 leads to an increased progression of renal disease by orchestrating inflammation and immune cell influx." (PMID 32977372, 2020). "Fifth, diseases known to elevate MIC-1/GDF-15 blood levels, such as renal disease and rheumatoid arthritis, are not comprehensively documented throughout all participating cohorts." (PMID 29628937, 2018). "Although some studies have been performed to find the correlation of plasma and urine GDF-15 levels with kidney disease, there is no study to look into its potential as prognostic marker for kidney disease after intervention." (PMID 26273671, 2015). "Finally, we observed that GDF-15, a member of the TGF beta superfamily, recently reported to be elevated in patients with renal disease, was one of the most strongly affected genes in our in vitro system." (PMID 23457584, 2013).